RN7SKP295 (RN7SK pseudogene 295)
Gene: Miscellaneous RNA gene on chromosome 5 (83,685,866 to 83,686,018, forward strand). Ensembl gene ENSG00000253073.
Homologues: Orthologues: chimpanzee 7SK (99% identical). Paralogues in human: RN7SKP187 (68% identical), RN7SKP210 (67% identical), RN7SKP156 (66% identical), 7SK (65% identical), RN7SKP80 (65% identical), RN7SKP174 (65% identical), RN7SKP55 (65% identical), RN7SKP48 (63% identical), RN7SKP252 (62% identical), RN7SKP251 (61% identical), RN7SKP118 (61% identical), RN7SKP178 (61% identical), and 283 more.